LINC00857 (long independently transcribed non-coding RNA 857)
Diseases named in the same sentence as LINC00857 in open-access papers (continued):
Sharing a sentence is not in itself a finding about the gene and the disease.
breast carcinoma (2 papers, 2020 to 2022). "Reduced expression of BLACAT1 in HNSCC; MALAT1, NEAT1 and PVT1 in NPC; FAM201A, PVT1 and LINC00857 in NSCLC; LINC00473, CCAT2and Rpph1 in EC; HOTAIR and LINC00958 in CRC; AFAP1-AS1 and LINC00511 in breast cancer were correlated with radiosensitivity." (PMID 36323697, 2022).
diffuse large B-cell lymphoma (2 papers, 2022). "A previous study showed that LINC00857 serves as an ceRNA that positively regulates CBX3 by negatively regulating miRNA370 expression, which promoted diffuse large B-cell lymphoma proliferation and lymphomagenesis." (PMID 35418193, 2022).
liver cancer (2 papers, 2019 to 2020). An epithelial or non-epithelial malignant neoplasm that arises from the liver. ",25, 26, 27, 28 For example, LINC00857 regulates cell proliferation in lung, bladder, gastric, esophageal, and liver cancer." (PMID 33312753, 2020).
pancreatic adenocarcinoma (2 papers, 2021 to 2025). "A comprehensive analysis of TCGA pancreatic adenocarcinoma (PAAD) sequencing data revealed significant positive correlations (FDR-adjusted p<0.05) between LINC00857 expression and key effector molecules of the canonical Wnt/β-catenin signaling pathway." (PMID 40303426, 2025). "Relationship between LINC00857 expression and clinicopathological properties of patients with pancreatic adenocarcinoma." (PMID 33661995, 2021).
colon adenocarcinoma (1 paper, 2021). "The present study aims to determine the expression pattern of LINC00857 in colon adenocarcinoma (COAD) patients and CRC cell lines." (PMID 34753396, 2021).
esophagus cancer (1 paper, 2019). "By analyzed our esophagus cancer Affymetrix array data (unpublished data), we found LINC00857 was increased in EAC as compared to normal esophagus tissues." (PMID 31085800, 2019). "We also evaluated the LINC00857 expression in a larger RNA-Seq data including 26 esophagus cancer cell lines." (PMID 31085800, 2019).
leukemia (1 paper, 2022). A malignant (clonal) hematologic disorder, involving hematopoietic stem cells and characterized by the presence of primitive or atypical myeloid or lymphoid cells in the bone marrow and the blood. "DLEU1 is linked to demethylation in leukemia, and LINC00857 is correlated to demethylation in NSCLC." (PMID 35571069, 2022).
osteosarcoma (1 paper, 2021). A usually aggressive malignant bone-forming mesenchymal neoplasm, predominantly affecting adolescents and young adults. "Increased EGR1 enhanced tumour‐suppressive effects of Scutellarin on osteosarcoma cells via transcriptionally downregulating LINC00857 expression." (PMID 34346162, 2021). "Taken together, these results suggest that EGR1/Linc00857/miR‐105‐5p/c‐Myc signal axis plays an essential role in antitumour effects of Scutellarin on osteosarcoma." (PMID 34346162, 2021). "Thus, our data suggest that EGR1/LINC00857/miR‐105‐5p/c‐Myc axis plays an important role in Scutellarin‐inhibited osteosarcoma cell growth." (PMID 34346162, 2021). "Thus, we ask whether LINC00857 contributes to Scutellarin‐induced c‐Myc downregulation in osteosarcoma cells." (PMID 34346162, 2021).
cancer (23 papers, 2016 to 2025). A tumor composed of atypical neoplastic, often pleomorphic cells that invade other tissues. "LINC00857, a long non-coding RNA, has been implicated in promoting cell proliferation across multiple cancer types and has been found to be aberrantly overexpressed in PC." (PMID 40303426, 2025). "LINC00857 expression was dramatically associated with TMB in ten cancers, with a positive correlation in six cancers including LUAD, KIRP, UCEC, LUSC, PCPG, UCS and a negative correlation in COAD, COADREAD, CHOL, DLBC." (PMID 36160408, 2022). "LINC00857 expression had a statistically inverse association with the immune cells in these eight cancers." (PMID 36160408, 2022). "We discovered that LINC00857 expression was dramatically associated with MSI in seven cancers, with a positive correlation in three cancers including BRCA, LIHC, TGCT and a negative correlation in COAD, COADREAD, KICH, DLBC." (PMID 36160408, 2022). "Our results suggest that LINC00857 expression was negatively associated with immune infiltrating cells in most of cancers, especially in eight LINC00857 high-expressing cancers." (PMID 36160408, 2022). "Our study discovered the pro-carcinogenic effect of LINC00857 in PAAD cancer cells, that is, LINC00857 was implicated in the malignancy of PAAD via acting as a ceRNA competitively targeting to miR-340-5p and thereby upregulating TGFA expression." (PMID 33661995, 2021). "Recently, LINC00857 was suggested to be closely associated with the tumorigenesis and progression of various cancers." (PMID 33680969, 2021). "Though LINC00857 expression was positively associated with MSI/TMB in some cancers, it may be still unsuitable for immunotherapy in consideration of the immune infiltrating cells status and immune checkpoint genes expression." (PMID 36160408, 2022). "We demonstrated that LINC00857 could potentially act as a diagnostic biomarker in eight cancers, including COAD, CHOL, KIRP, HNSC, LUAD, LIHC, PAAD and STAD." (PMID 36160408, 2022). "In summary, LINC00857 expression was closely correlated with an immunosuppressive microenvironment and may be a novel diagnostic and prognostic biomarker for diverse cancers." (PMID 36160408, 2022). "Consequently, these results support that LINC00857 may act as a new diagnostic biomarker for many cancer types." (PMID 36160408, 2022). "LINC00857 might act as a novel diagnostic and prognostic biomarker for diverse cancers." (PMID 36160408, 2022). "LINC00857 exerts oncogenic effect in varying cancers through promoting cell proliferation, invasion and migration." (PMID 38721812, 2024). "Through bioinformatics analysis, we examined the expression state and methylation site of LINC00857 in LUAD and further investigated the properties of LINC00857 as a competitive endogenous RNA in the cancer progression." (PMID 38721812, 2024). "Here, we integrated data from several databases to analyze the characteristics of LINC00857 in pan-cancer." (PMID 36160408, 2022). "We explored the expression levels of LINC00857 in 31 healthy tissues and 21 cancer cell lines through the Sangerbox database." (PMID 36160408, 2022). "LINC00857 is considered to be an oncogenic lncRNA that promotes proliferation and metastasis of cancer cells in pancreatic, colorectal and breast cancers, and it regulates apoptosis and autophagy." (PMID 36171881, 2022). "To ascertain the expression levels of LINC00857 in normal and cancers samples, we obtained data from TCGA, CCLE and GTEx datasets." (PMID 36160408, 2022). "In the present analysis, we elucidated the expression, prognostic value and immune characteristics of LINC00857 in pan-cancer using bioinformatics." (PMID 36160408, 2022). "We found that LINC00857 was overexpressed and correlated with a poor prognosis in a variety of cancers." (PMID 36160408, 2022). "Multiple studies have reported that LINC00857 has a high relevance with the development and progression of diverse cancers." (PMID 36160408, 2022).
cancer (continued). "We characterized the expression levels of LINC00857 in cancers and corresponding normal samples using the TCGA and GTEx datasets." (PMID 36160408, 2022). "LINC00857 (long intergenic non‐protein‐coding RNA 857) has been reported to play a carcinogenic factor in several human cancers and regulated cancer cell growth, death and metastasis." (PMID 34346162, 2021). "Although there are already studies on LINC00857 in other cancers, the physiological function of LINC00857 in the progression of PC is still largely unclear." (PMID 33680969, 2021). "Regarding the up-regulated lncRNAs, only a low number of them have been previously implicated in cancer, such as the up-regulated CASC15, LINC00662, LINC01272, LINC00857, LINC00092, LINC00673 and the down-regulated LINC00657, LINC01087 and LINC00993." (PMID 32753692, 2020). "LINC00857 (long intergenic non‐protein coding RNA 857) has been discovered to be a crucial factor in the regulation of cancer development." (PMID 32918541, 2020). "Colony‐forming assays showed that LINC00857 knockdown impaired growth of cancer cells marked by a reduction in the number of colonies formed by T24 and UM‐UC‐3 cells (P = .01 and P = .005, resp.)." (PMID 29856124, 2018). "To explore if LINC00857 is expressed in other types of cancer, we downloaded 6,220 cancer RNA-Seq expression data from MiTranscriptome." (PMID 26862852, 2016). "Contrary to knockdown experiments, overexpression of LINC00857 promoted cancer cell colony formation, cell proliferation and invasion in SK-LU-1 cells." (PMID 26862852, 2016). "A significant decrease in cell proliferation in both H1299 and H838 cell lines and reduced cancer cell invasion (as measured by Boyden chamber matrigel invasion assays) was noted when LINC00857 was knocked down." (PMID 26862852, 2016). "Based on our previous study, LINC00857 plays a cancer-promoting role in PC18." (PMID 40303426, 2025). "Research has confirmed the involvement of various lncRNAs in cancer initiation and progression, notably LINC00857, which is overexpressed in a range of cancers and regulates multiple cellular activities related to cancer development such as invasion, migration, growth, and apoptosis." (PMID 38849442, 2024). "By contrast, LINC00857 was highly expressed in most cancer cell lines, which may imply its effect on the malignant phenotype of cancer cells." (PMID 36160408, 2022). "By simultaneous analysis of four databases (Sangerbox 3.0, ACLBI, StarBase V3.0 and Lnc2Cancer 3.0), we found that the expression levels of LINC00857 were markedly higher in eight cancers than in the adjacent normal tissues including HNSC, CHOL, COAD, KIRP, STAD, LIHC, PAAD and LUAD." (PMID 36160408, 2022). "In addition, the present research noticed that LINC00857 expression was negatively related to the immune score and microenvironment score in these eight cancers." (PMID 36160408, 2022). "Several studies reported that LINC00857 participates in the development of other malignant tumors." (PMID 35418193, 2022). "Significantly, our data confirmed a negative association between LINC00857 expression and TMB/MSI/NEO in COAD, suggesting that immune checkpoint inhibitors may have poor response in those cancer patients with high-expression of LINC00857." (PMID 36160408, 2022). "GSEA findings revealed that knockdown of LINC00857 triggered the ferroptosis pathway, which might account for how LINC00857 facilitated cancer growth." (PMID 36160408, 2022). "Furthermore, stage plot in the Lnc2Cancer 3.0 and GEPIA2 databases suggest that LINC00857 expression was strikingly correlated with the cancer pathological stages." (PMID 36160408, 2022). "Nevertheless, most studies on LINC00857 have been restricted to one specific cancer type." (PMID 36160408, 2022). "Thus, it is valuable to delve into the oncogenic roles of LINC00857 in pan-cancer, providing novel orientations and tactics for the diagnosis and treatment of cancers." (PMID 36160408, 2022).
cancer (continued). "In conclusion, these data validated that LINC00857 expression was highly associated with the prognosis in multiple cancers, implicating that LINC00857 may be a reasonable biomarker to evaluate the prognosis of many cancers." (PMID 36160408, 2022). "LINC00857 likely acts as an oncogene contributing to cancer development." (PMID 36160408, 2022). "Collectively, our research integrally analyzed the oncogenic roles of LINC00857 in pan-cancer." (PMID 36160408, 2022). "Previously, LINC00857 has been reported to be highly expressed in other cancers." (PMID 33680969, 2021). "One previous study reported that the overexpression of LINC00857 could enhance the proliferation, invasion and colony formation of cancer cells." (PMID 34753396, 2021). "Although several studies have suggest that LINC00857 play a key role in cancer, its functions in response to Scutellarin remain unclear." (PMID 34346162, 2021). "Overexpression of LINC00857 increased cancer cell proliferation, colony formation and invasion." (PMID 26862852, 2016). "The LINC00857 genomic locus was not amplified, thus we hypothesize that the cancer specific LINC00857 expression may be mediated by specific transcription factors coupled with changes in histone and DNA modification (H3K27 acetylation) in its gene promoter." (PMID 26862852, 2016). "These indicated that LINC00857 was highly expressed in some types of cancer especially in lung AD (vs. normal) and could be potential useful as lung AD specific marker." (PMID 26862852, 2016). "LINC00857 is abnormally expressed in several cancers, which may impact on the tumor biology." (PMID 38721812, 2024). "Besides, LINC00857 may also affect cancer growth by mediating lipid metabolism, glycolysis and multiple signaling pathways." (PMID 36160408, 2022). "To uncover the potential proteins or pathways affected by LINC00857, we performed p-kinase protein antibody array and receptor tyrosine kinase phosphorylation antibody array analyses, which include more than 100 proteins covering most of the cancer-related pathways." (PMID 33312753, 2020). "Various lncRNAs such as LINC00857, MIR17HG, NKX2-1-AS1, LINC01234, and FAM225A have been found to manipulate specific miRNAs to influence cancer cell behavior." (PMID 39172101, 2024). "The cancer genome atlas (TCGA) data showed a significant positive correlation between the expression of HSF1 and LINC00857." (PMID 36010849, 2022). "As a key molecule linking LINC00857 and TGFA, miR-340-5p has attracted extensive attentive in human cancer." (PMID 33661995, 2021). "In order to confirm the upregulation of LINC00857 in CRC, we collected 50 tumor tissues and adjacent non-carcinoma samples from 50 CRC patients." (PMID 34753396, 2021). "To examine the functional role of LINC00857, we performed small interfering RNA (siRNA)-mediated knockdown in H1299 and H838, two lung LUAD cancer cells, which contains high levels of the endogenous LINC00857 transcript." (PMID 26862852, 2016). "Consequently, by affecting the ANXA11 promoter, LINC00857 promotes the activation of the HSF1/LINC00857/ANXA11 signalling axis, which enhances the proliferation and spread of cancer cells." (PMID 39690143, 2024). "Interestingly, combining the bioinformatics and qPCR verification, we eventually discovered that LINC00857 probably exert its oncogenic effects by mediating PIWIL4 expression, which presented oncogenic potential in multiple cancer types." (PMID 36160408, 2022). "The LINC00857/PIWIL4 axis may be predictive biomarkers for immunotherapy and valuable molecular targets for malignant tumors." (PMID 36160408, 2022). "LINC00857 and LINC00261 are also related to cancer invasion and migration." (PMID 35571069, 2022). "LINC00857/PIWIL4 axis may be predictive biomarkers for immunotherapy and valuable molecular targets for malignant tumors." (PMID 36160408, 2022).
cancer (continued). "Although aberrant LINC00857 expression may play a key role in oncogenesis, no research has analyzed the pan-cancer oncogenic roles of LINC00857, particularly in tumor immunology." (PMID 36160408, 2022). "Similarly, our study revealed a negative correlation between LINC00857 expression and immune score in these cancers." (PMID 36160408, 2022).
tumor (19 papers, 2016 to 2025). "In the purpose of revealing LINC00857 expression in LUAD, as revealed by bioinformatics analysis, LINC00857 level in tumor tissue was prominently upregulated compared with the paired normal one in TCGA database." (PMID 38721812, 2024). "We sought to unveil function of epigenetic changes of LINC00857 in LUAD, its biological effects on LUAD tumor, and the possible molecular mechanism underlying the LUAD occurrence and metastasis." (PMID 38721812, 2024). "The methylation level of LINC00857 in LUAD tumor tissue was prominently lower than in matched normal tissue." (PMID 38721812, 2024). "Increasing studies have indicated that LINC00857 acts as a miRNAs sponge to regulate tumour progression." (PMID 34346162, 2021). "In our recent publication, knocking down LINC00857 reduced tumor cell proliferation, colony formation, migration, invasion in vitro, and tumor growth in vivo." (PMID 33312753, 2020). "Further, we found LINC00857 regulates cell proliferation and tumor growth via cell cycle regulation." (PMID 33312753, 2020). "In our study, LINC00857 expression in the primary tumor was shown to predict MIBC progression and response to chemotherapy." (PMID 29856124, 2018). "Functional characterization indicated that LINC00857 plays an important role in tumor proliferation, migration and invasion." (PMID 26862852, 2016). "knockdown of LINC00857 with siRNAs decreased tumor cell proliferation, colony formation, migration and invasion in vitro, as well as tumor growth in vivo." (PMID 26862852, 2016). "In summary, LINC00857 knockdown repressed LUAD tumor growth in vivo." (PMID 38721812, 2024). "The combination of apigenin (40 μM) and a low concentration of OXA (5 μM) on OSCC revealed that apigenin could inhibit the pro-tumor metastatic effect of OXA through downregulating the expression of LINC00857." (PMID 39518052, 2024). "The effects of LINC00857 on tumor growth were also investigated in nude mice models." (PMID 38721812, 2024). "LINC00857 level was detected in clinical LUAD tissue and matched para‐cancerous tissue, as well as cell lines (BEAS‐2B, A549, H1299, PC‐9, H838, and NCI‐H23), through qRT‐PCR, and we uncovered that LINC00857 level in LUAD tumor tissue was markedly higher than in corresponding para‐cancerous tissue." (PMID 38721812, 2024). "qRT-PCR analysis revealed the significant upregulation of LINC00857 in CRC tumor samples." (PMID 34753396, 2021). "In addition, the GEPIA database revealed that LINC00857 exhibited high expression in 179 PC samples compared with 171 non-tumor samples." (PMID 33680969, 2021). "In summary, LINC00857 influenced tumor cell proliferation, colony formation, apoptosis, as well as migration and invasion which may be via affecting MET/STAT3/c-Myc/CREB oncoproteins." (PMID 31085800, 2019). "Taken together, LINC00857 affecting tumor cell proliferation, colony formation, apoptosis, as well as migration and invasion may be via MET, STAT3, c-Myc and CREB oncoproteins." (PMID 31085800, 2019). "Mechanistic analyses indicated that LINC00857 mediates tumor progression via cell cycle regulation." (PMID 26862852, 2016). "In addition, we also confirmed the effects of LINC00857 in promoting tumor growth in nude mice." (PMID 38721812, 2024). "LINC00857 Knockdown constrains in vitro proliferation, migration, invasion, and lymph node metastasis of LUAD cells, and impairs in vivo tumor growth." (PMID 38721812, 2024). "The co-regulation of LINC00857, LINC00968, LINC00663, and ITGA9-AS1 on SOX2 suggested their potential contributions in aberrant sialylation process during tumor progression." (PMID 38632255, 2024). "The results showed that AC005332.6, AC090114.2, LINC00857, and LINC02041 were all upregulated in tumor cells, while AL117382.1 was downregulated in tumor cells (p < 0.05)." (PMID 36359832, 2022). "Immunohistochemistry of tumor specimens revealed lower Ki-67 and PCNA expression in the LINC00857 knockdown group compared with the high LINC00857 expression." (PMID 35418193, 2022).
tumor (continued). "LINC00857 was upregulated in CRC and correlated with tumor grade and microsatellite instability status." (PMID 36010849, 2022). "The cell apoptosis was also induced upon LINC00857 knockdown, indicating LINC00857 may be involved in EAC tumor growth." (PMID 31085800, 2019).
adenocarcinoma (1 paper, 2019). A common cancer characterized by the presence of malignant glandular cells. "We found 19/26 cell lines have higher LINC00857 expression level more than 1 FPKM value, and OE33, an adenocarcinoma, was the highest one." (PMID 31085800, 2019).